Y_RNA (Y RNA )
Gene: Miscellaneous RNA gene on chromosome 19 (49,566,672 to 49,566,772, forward strand). Ensembl gene ENSG00000207073.
Homologues: Orthologues: chimpanzee Y_RNA (99% identical), macaque Y_RNA (92% identical). Paralogues in human: Y_RNA (88% identical), RNY3 (87% identical), Y_RNA (87% identical), RNY3P1 (86% identical), Y_RNA (86% identical), Y_RNA (85% identical), RNY3P16 (84% identical), RNY3P5 (84% identical), Y_RNA (84% identical), RNY3P14 (83% identical), RNY3P7 (83% identical), Y_RNA (83% identical), and 94 more.